CDK5RAP3 (CDK5 regulatory subunit associated protein 3)
Description:
Substrate adapter of E3 ligase complexes mediating ufmylation, the covalent attachment of the ubiquitin-like modifier UFM1 to substrate proteins, and which is involved in various processes, such as ribosome recycling and reticulophagy (also called ER-phagy). As part of the UREL complex, plays a key role in ribosome recycling by promoting mono-ufmylation of RPL26/uL24 subunit of the 60S ribosome. Ufmylation of RPL26/uL24 occurs on free 60S ribosomes following ribosome dissociation: it weakens the junction between post-termination 60S subunits and SEC61 translocons, promoting release and recycling of the large ribosomal subunit from the endoplasmic reticulum membrane. Ufmylation of RPL26/uL24 and subsequent 60S ribosome recycling either take place after normal termination of translation or after ribosome stalling during cotranslational translocation at the endoplasmic reticulum. Within the UREL complex, CDK5RAP3 acts as a substrate adapter that constrains UFL1 ligase activity to mono-ufmylate RPL26/uL24 at 'Lys-134'. The UREL complex is also involved in reticulophagy in response to endoplasmic reticulum stress by promoting ufmylation of proteins such as CYB5R3, thereby promoting lysosomal degradation of ufmylated proteins. Also acts as a regulator of transcription: negatively regulates NF-kappa-B-mediated gene transcription through the control of RELA phosphorylation. Also regulates mitotic G2/M transition checkpoint and mitotic G2 DNA damage checkpoint. May also play a role in the rupture of the nuclear envelope during apoptosis. May regulate MAPK14 activity by regulating its dephosphorylation by PPM1D/WIP1. Required for liver development (By similarity). (Microbial infection) May be negatively regulated by hepatitis B virus large envelope protein mutant pre-s2 to promote mitotic entry.
Synonyms: IC53; LZAP; OK/SW-cl.114; PP1553; MST016; FLJ13660; C53; HSF-27
Tractability: PROTAC: UniProt records ubiquitination sites on it; ubiquitination databases record sites on it; its protein half-life has been measured.
Gene: Protein-coding gene on chromosome 17 (47,967,810 to 47,981,781, forward strand). Ensembl gene ENSG00000108465.
Subcellular location: Endoplasmic reticulum membrane; Cytoplasm; Nucleus; Cytoplasm, cytoskeleton, microtubule organizing center, centrosome; Cytoplasm, cytoskeleton
Subcellular location (Human Protein Atlas): Cytosol; Nucleoli; Vesicles
Gene Ontology:
Molecular function: cyclin binding; MDM2/MDM4 family protein binding; mitogen-activated protein kinase binding; NF-kappaB binding; protein binding; protein kinase binding; ubiquitin-like ligase-substrate adaptor activity; ubiquitin-like protein ligase binding
Biological process: apoptotic nuclear changes; cell population proliferation; endoplasmic reticulum unfolded protein response; mitotic G2 DNA damage checkpoint signaling; mitotic G2/M transition checkpoint; negative regulation of MAP kinase activity; negative regulation of protein catabolic process; negative regulation of protein kinase activity by regulation of protein phosphorylation; negative regulation of protein phosphorylation; negative regulation of protein serine/threonine kinase activity; positive regulation of protein localization to nucleus; positive regulation of protein ubiquitination; positive regulation of reticulophagy; positive regulation of ubiquitin-dependent protein catabolic process; protein ufmylation; regulation of phosphatase activity; rescue of stalled ribosome; ribosome disassembly; brain development; definitive erythrocyte differentiation; liver development; regulation of cyclin-dependent protein serine/threonine kinase activity; regulation of mitotic cell cycle; regulation of neuron differentiation; and 1 more
Cellular component: centrosome; cytoplasm; cytosol; endoplasmic reticulum membrane; membrane; microtubule; nucleolus; nucleus; protein-containing complex; transferase complex; endomembrane system; cytoskeleton
Genetic constraint (gnomAD): Loss-of-function variants: 50 observed, 65.55 expected, observed/expected ratio (o/e) 0.76, 90% interval 0.61 to 0.96. The upper end of that interval is the gene's LOEUF score, 0.96, which puts it in group 4 of 6, group 1 being the genes least tolerant of losing a copy. Missense variants: 493 observed, 591.21 expected, observed/expected ratio (o/e) 0.83, 90% interval 0.77 to 0.9. Synonymous variants: 210 observed, 241.99 expected, observed/expected ratio (o/e) 0.87, 90% interval 0.77 to 0.97.
Homologues: Orthologues: macaque CDK5RAP3 (98% identical), chimpanzee CDK5RAP3 (93% identical), dog CDK5RAP3 (93% identical), rabbit CDK5RAP3 (89% identical), mouse Cdk5rap3 (88% identical), rat Cdk5rap3 (88% identical), guinea pig CDK5RAP3 (82% identical), pig CDK5RAP3 (79% identical), zebrafish cdk5rap3 (62% identical), tropical clawed frog cdk5rap3 (59% identical), Caenorhabditis elegans cdkr-3 (38% identical), Drosophila melanogaster CG30291 (35% identical).
Diseases named in the same sentence as CDK5RAP3 in open-access papers:
CDK5RAP3 is named in the same sentence as 53 diseases in open-access papers, as found by Europe PMC text mining. Sharing a sentence is not in itself a finding about the gene and the disease. The quoted sentences say what the papers report.
gastric cancer (14 papers, 2018 to 2024). A primary or metastatic malignant neoplasm involving the stomach. "Low expression of UFM1 and CDK5RAP3 was associated with poor prognosis, which was independent predictor to predict overall survival of gastric cancer patients." (PMID 39247188, 2024). "The use of an MMP2 inhibitor attenuated colony formation caused by gastric cancer cells with low expression of CDK5RAP3." (PMID 35999359, 2023). "The evidence for the immunosuppression of gastric cancer with a specific phenotype associated with CDK5RAP3 still needs to be further explored." (PMID 35999359, 2023). "MMP2 inhibitor also attenuated the increased invasion and migration ability of gastric cancer cells caused by low expression of CDK5RAP3." (PMID 35999359, 2023). "We have demonstrated that CDK5RAP3 exerts a tumour suppressor effect in gastric cancer, but its role in regulating tumour-associated macrophages (TAMs) has not yet been reported." (PMID 35999359, 2023). "Analysis of factors associated with the expression of CDK5RAP3 and UFM1 in gastric cancer tissues showed that the CDK5RAP3 and UFM1 expression significantly correlated with BMI, lymph node metastasis, depth of invasion and pathological TNM stage." (PMID 36387125, 2022). "It was suggested that UFM1 was positively correlated with CDK5RAP3 and its low expression was associated with poorer prognosis of gastric cancer." (PMID 36387125, 2022). "The loss of CDK5RAP3 expression in gastric cancer cells induces the recruitment of TAMs into tumour tissues and might cause them to evolve into a cancer-promoting phenotype." (PMID 35999359, 2023). "CDK5RAP3 is associated with a better prognosis in patients with gastric cancer." (PMID 35999359, 2023). "Professor Chang-Ming Huang and colleagues confirmed that in gastric cancer, CDK5RAP3 inhibited nuclear transcription of NF-κB, thereby decreasing the secretion of cytokines IL4 and IL10 and blocking the polarization of M2 macrophages." (PMID 38643190, 2024). "CDK5RAP3 suppresses gastric cancer development by inhibiting AKT/GSK-3β phosphorylation and negatively regulating Wnt/β-catenin signaling." (PMID 37947621, 2023). "CCL2 is overexpressed in gastric cancer with low CDK5RAP3 expression, and the expression of the two is significantly negatively correlated." (PMID 35999359, 2023). "In short, the method of restoring the expression of CDK5RAP3 in gastric cancer to regulate MMPs from macrophages is expected to provide a new perspective for immunotherapy to reduce the progression and metastasis of gastric cancer." (PMID 35999359, 2023). "Consistently, we demonstrated that cytokines mediated by low CDK5RAP3 expression in gastric cancer promoted the polarization of M2-like macrophages." (PMID 35999359, 2023). "The addition of an MMP2 inhibitor to the coculture system significantly inhibited the EMT process of gastric cancer induced by low expression of CDK5RAP3." (PMID 35999359, 2023). "The neutralizing antibodies against IL4 and IL10 also reduced the upregulation of CD86+ macrophages induced by the overexpression of CDK5RAP3 in gastric cancer cells." (PMID 35999359, 2023). "We randomly took 5 visions for each gastric cancer specimen, a total of 140 vision to calculate the correlation between the number of TAMs and the expression of CDK5RAP3." (PMID 35999359, 2023). "Next, the TIMER database was used to visualize the correlation between CDK5RAP3 and the levels of immune infiltration in gastric cancer." (PMID 35999359, 2023). "CDK5RAP3 reduces the recruitment of circulating monocytes to infiltrate tumour tissue by inhibiting the CCL2/CCR2 axis in gastric cancer." (PMID 35999359, 2023). "The proportion of CD86+ TAMs was increased under coculture conditions with gastric cancer cells overexpressing CDK5RAP3." (PMID 35999359, 2023). "Our research illustrates the crosstalk between the expression of CDK5RAP3 in gastric cancer and TAMs in TME." (PMID 35999359, 2023).
gastric cancer (continued). "In the present study, we proved that the expression of CDK5RAP3 in gastric cancer cells not only inhibited the infiltration of macrophages but also inhibited the polarization of TAMs to the M2 phenotype." (PMID 35999359, 2023). "The same pattern was validated in AGS gastric cancer cells with stable overexpression or knockdown of CDK5RAP3." (PMID 35999359, 2023). "The mRNA levels of CCL2 were decreased in gastric cancer cells overexpressing CDK5RAP3 but increased in gastric cancer cells with downregulation of CDK5RAP3." (PMID 35999359, 2023). "Our results demonstrated that mixed phenotypic TAMs, especially TAMs mediated by low expression of CDK5RAP3 in gastric cancer, are an important functional mediator of maintaining the progression of gastric cancer." (PMID 35999359, 2023). "PDTC also reduced the upregulation of CD86+ macrophages induced by gastric cancer cells overexpressing CDK5RAP3." (PMID 35999359, 2023). "In gastric cancer tissues with high CDK5RAP3 expression, the number of CD206 CT and CD206 IM cells decreased." (PMID 35999359, 2023). "In general, the low expression of CDK5RAP3 in gastric cancer can promote the secretion of CCL2, which recruits monocytes to infiltrate the tumour microenvironment through CCL2/CCR2 signalling." (PMID 35999359, 2023). "The low expression of CDK5RAP3 in gastric cancer cells promotes the secretion of MMP2 by macrophages, thereby enhancing the proliferation, invasion and migration ability of gastric cancer cells." (PMID 35999359, 2023). "Then, we divided gastric cancer cases into 4 groups based on the expression of CDK5RAP3 and the number of TAM-positive markers." (PMID 35999359, 2023). "Our discovery expands the knowledge system about the role of CDK5RAP3 in gastric cancer and is different from previous studies that were limited to gastric cancer cells themselves, but aimed at its relationship with the TME of gastric cancer." (PMID 35999359, 2023). "Our previous studies have demonstrated that CDK5RAP3 negatively regulates the EMT process of gastric cancer cells." (PMID 35999359, 2023). "We further performed multiple immunofluorescence analysis on 28 gastric cancer specimens to reveal the distribution landscape of CDK5RAP3 and TAMs in gastric cancer." (PMID 35999359, 2023). "Under the conditions of cocultivation with TAMs, the low expression of CDK5RAP3 significantly promoted the proliferation of gastric cancer cells." (PMID 35999359, 2023). "We identified that IL4 and IL10 were significantly enriched in the KEGG ‘cytokine-cytokine receptor interaction pathway’, which is significantly activated in gastric cancer with low CDK5RAP3 expression." (PMID 35999359, 2023). "PDTC (an NF-κB inhibitor) attenuated the upregulation of CD206+ macrophages induced by low-expressing CDK5RAP3 gastric cancer cells." (PMID 35999359, 2023). "The phosphorylation of NF-κB p65 at Ser536 was increased in gastric cancer cells with low CDK5RAP3 expression but decreased in cells overexpressing CDK5RAP3." (PMID 35999359, 2023). "The levels of IL4 and IL10 were significantly reduced in gastric cancer cells overexpressing CDK5RAP3." (PMID 35999359, 2023). "Rescue studies have shown that neutralizing antibodies to IL4 and IL10 can attenuate the upregulation of CD206+ macrophages induced by gastric cancer cells with low CDK5RAP3 expression." (PMID 35999359, 2023). "In recent years, we have performed multiple studies on cyclin-dependent kinase 5 (CDK5) regulatory subunit-associated protein 3 (CDK5RAP3, also known as C53/LZAP) in gastric cancer." (PMID 35999359, 2023). "According to a number of studies, CDK5RAP3 plays a major role in controlling Wnt/β‐catenin, Akt and other signalling pathways in gastric cancer." (PMID 35509151, 2022). "This study mainly explored the impact of the coexpression level of UFM1 and CDK5RAP3 on the clinicopathological parameters of gastric cancer patients and its prognostic significance, providing a preliminary basis for further research." (PMID 36387125, 2022).
gastric cancer (continued). "The association of different CDK5RAP3 and UFM1 expression levels in gastric cancer tissues with clinicopathological factors." (PMID 36387125, 2022). "The association of CDK5RAP3 and UFM1 expression in gastric cancer tissues with clinicopathological factors." (PMID 36387125, 2022). "Analysis of 7 GEO databases (GSE13861, GSE54129, GSE19826, GSE79973, GSE13911, GSE51575, GSE29272) showed that CDK5RAP3 expression was low in gastric cancer." (PMID 36387125, 2022). "IHC staining of cancerous and paracancerous tissues from gastric cancer patient showed that CDK5RAP3 and UFM1 protein expression in cancerous samples were both lower than that in paracancerous." (PMID 36387125, 2022). "Meanwhile, CDK5RAP3, the satellite component of the UFMylation system, has been shown to suppress the development of gastric cancer via inhibiting the phosphorylation of Akt/GSK-3β and negatively regulating Wnt/β-catenin signaling." (PMID 35884562, 2022). "The expression level of CDK5RAP3 is significantly reduced both in gastric cancer and in GNEC tissues which is correlated with TNM stage, poor prognosis, invasion depth, and lymph node metastasis." (PMID 34722315, 2021). "Another CDK5RAP3 isoform IC53d is shown to be up-regulated in human gastric cancer tissues and its overexpression promotes tumorigenesis in vitro and in vivo." (PMID 34722315, 2021). "Our previous study demonstrated that CDK5RAP3 expression was downregulated in gastric cancer, resulting in inhibition of Wnt/β-catenin signaling." (PMID 31728130, 2019). "In gastric cancer, CDK5RAP3 acts as a tumor suppressor through inactivation of Wnt/β-catenin signaling, and downregulation of this protein in gastric cancer indicates poor prognosis." (PMID 31061682, 2019). "Our previous study demonstrated that CDK5RAP3 exerts a tumor suppressive function in gastric cancer by inhibiting β-catenin, a major driver of cancer development." (PMID 31728130, 2019). "Significantly, MCM6 and CDK5RAP3 together influenced the prognostic value of patients with gastric cancer, which provided clinical support that MCM6 is involved in the tumor suppression mechanism of CDK5RAP3." (PMID 31528213, 2019). "When CDK5RAP3 expression was low, gastric cancer patients with low expression of MCM6 had a better prognosis than did those with high CDK5RAP3 expression (P<0.05)." (PMID 31528213, 2019). "Our primary study indicated that CDK5RAP3 expression was decreased in gastric cancer, and that cancer cell proliferation and invasion were suppressed through the inhibition of Wnt/β-catenin signaling." (PMID 31528213, 2019). "Our previous study found that the downregulation of CDK5RAP3 leads to poor prognosis in gastric cancer via inhibition of Wnt/β-catenin signaling." (PMID 31528213, 2019). "All of these studies demonstrated that CDK5RAP3 acted as an important tumor suppressor in gastric cancer." (PMID 31528213, 2019). "Following CDK5RAP3 overexpression or knock down, CDK5RAP3 signaling pathways were investigated in gastric cancer cells by Western Blotting." (PMID 29540196, 2018). "To further verify the associations among CDK5RAP3, p-GSK-3β (Ser9) and p-AKT (Ser473), we detected the expression of CDK5RAP3, p-GSK-3β (Ser9) and p-AKT (Ser473) in the 209 gastric cancer samples using IHC." (PMID 29540196, 2018). "Our study demonstrated that the expression of p-AKT (Ser473) and p-GSK-3β (Ser9) was negatively correlated with CDK5RAP3 in stable gastric cancer cell lines." (PMID 29540196, 2018). "Although CDK5RAP3 has been shown to negatively regulate the Wnt/β-catenin signaling pathway in gastric cancer by repressing GSK-3β phosphorylation, its in-depth mechanism has not been determined." (PMID 29540196, 2018). "We also investigated the prognostic value of CDK5RAP3 in gastric cancer and showed that it depended on AKT activity." (PMID 29540196, 2018).